S100A16 (S100 calcium binding protein A16)
Diseases named in the same sentence as S100A16 in open-access papers (continued):
Sharing a sentence is not in itself a finding about the gene and the disease.
tumor (continued). "Similar to the in vitro results, S100A16 was found to promote the growth of tumour xenografts in BALB/C nude mice." (PMID 37509106, 2023). "Like most members of the S100 family, S100A16 was firstly reported as a regulatory factor related to malignant transformation and tumor development 6, 30-32." (PMID 37928262, 2023). "The purpose of this study was to investigate the expression of S100A16 in BC tumor cells by immunohistochemistry and to evaluate the tumor aggressiveness and its prognostic impact on patients with BC who underwent RC." (PMID 37833982, 2023). "Taken together, these findings show that PI3K/Akt signaling is a common tumor-promoting pathway for S100A16 and AHNAK2." (PMID 37833982, 2023). "Further, a gradual loss of S100A16 mRNA and protein levels was found during the progression of OSCC, indicating a possible tumour suppressive function for S100A16 in OSCC." (PMID 37509106, 2023). "Our research revealed a statistically significant (p < 0.05) increase in the levels of S100A16 protein in 63 tumor specimens compared to the corresponding cervical paracancerous specimens." (PMID 37978469, 2023). "Elucidating the mechanism of action of S100A16 in BC will confirm its role as a tumor-promoting factor." (PMID 37833982, 2023). "This indicated that S100A16 possesses a dual role, acting as a tumor suppressor or tumor promoter in different malignancies." (PMID 37151881, 2023). "S100A16, a calcium-binding protein belonging to the S100 superfamily, is mostly involved in tumor progression." (PMID 35061207, 2022). "To evaluate the effect of S100A16 expression on the tumor microenvironment, we analyzed connection among S100A16 and specific immune cells." (PMID 36176934, 2022). "In vivo and in vitro analyses revealed that ectopic overexpression of S100A16 promotes tumor formation and migration, whereas S100A16 knockdown remarkably reduced tumor growth and migration." (PMID 34650982, 2021). "Through the analysis of 182 TCGA specimens, it was found that high or low expression of S100A16 was significantly correlated with Primary tumor site, stage, and grade of PDAC (P < 0.05)." (PMID 33912559, 2021). "According to the TIMER database analysis, CD8+ T cells were negatively correlated with S100A16, suggesting that S100A16 was correlated with tumor immunity." (PMID 33912559, 2021). "Together, S100A16 upregulation is both necessary and sufficient to trigger GC tumor growth, proliferation, and migration, which suggest that it functions as a considerable oncogene in GC." (PMID 34650982, 2021). "As we expected, the size and weight of tumor grafts isolated from lenti-S100A16 group were obviously larger than that in the control group after 26 days of tumor implantation." (PMID 34650982, 2021). "The growth rate of tumor grafts in the mice from lenti-S100A16 group was significantly faster than that in the control-group from the 10th day of SGC-7901 infection." (PMID 34650982, 2021). "In parallel, S100A16 over-expression reduced tumorigenic abilities (tumor incidence and tumor volume) of H357 cells in NOD/SCID mice." (PMID 26353754, 2015). "S100A16 over-expression also suppressed tumorigenesis of H357 cells in a mouse xenograft model and the resulting tumor xenografts displayed features/expression of increased differentiation and reduced proliferation/self-renewal." (PMID 26353754, 2015). "Positive correlation between S100A16 protein level and tumor differentiation, as found in the current study, pointed to a functional role of S100A16 in the regulation of keratinocyte differentiation." (PMID 26353754, 2015). "Of this protein family, S100A14 and S100A16 are also believed to play an important role in tumor progression." (PMID 25884418, 2015). "Moreover, gene expression analysis showed that the expressions of KRT8 and S100A16 were significantly increased in tumor tissues, while the expressions of COL4A3, SMAD9, MAP3K8 and CCDC146 were decreased." (PMID 41239716, 2025).
tumor (continued). "Reverse transcription-quantitative polymerase chain reaction validation results demonstrated that KRT8 and S100A16 were significantly upregulated in tumor tissues, while COL4A3 and SMAD9 expression was downregulated, which was consistent with the TCGA-LUAD database analysis." (PMID 41239716, 2025). "The molecular analysis further showed that circ_0036627 increased S100A16 expression by sponging microRNA‐145 (miR‐145), a tumour‐suppressive miRNA that could significantly attenuate PC cell proliferation, migration, invasion and GEM resistance." (PMID 38924205, 2024). "Through the profiling of PC patient cohort dataset in the database UALCAN, S100A16 expression was also significantly elevated in PC tumour tissues when compared to normal tissues and the relative levels of S100A16 were higher in Grade 2 and 3 tumour samples when compared to Grade 1 samples." (PMID 38924205, 2024). "HE staining showed that the number of tumor cells increased and some areas showed infiltration and accumulation of inflammatory cells in inhibitors and oe-S100A16 group, while sh-lnc group decreased the tumor cells and the infiltration and accumulation of inflammatory cells." (PMID 38370382, 2024). "Quantitative analysis demonstrated that S100A16 significantly enlarged the tumor volume in vivo." (PMID 37151881, 2023). "S100A16 is expected to serve as a biomarker for the aggressive tumor phenotype." (PMID 37833982, 2023). "The oncogenic efficiency of S100A16 was confirmed and evaluated by tumor volume and tumor weight." (PMID 37151881, 2023). "Based on drug sensitivity data in the GDSC database, our study predicted the chemotherapy sensitivity of each tumor specimen using the R package pRRophetic to further investigate any relation between S100A16 expression levels and sensitivity to common chemotherapeutic drugs." (PMID 37978469, 2023). "S100A16 expression in tumor was first screened in GEPIA database." (PMID 37151881, 2023). "Moreover, there are more than one E3 ubiquitin ligase for LATS1, further investigations are needed to characterize other CUL4A adaptors or additional E3 ligases in the regulation of tumor progression by S100A16." (PMID 37151881, 2023). "Additional analysis revealed that the expression of S100A16 was elevated in RCC tumor tissues." (PMID 36176934, 2022). "The TIMER database shows that the expression of S100A16 is associated with immune infiltration and may play an important role in promoting tumor cell immune escape in the RCC tumor microenvironment." (PMID 36176934, 2022). "We found that S100A16 was highly expressed in the majority of tumor tissues." (PMID 36176934, 2022). "By modulating the PI3K/AKT signaling pathway, S100A16 may boost the proliferation, migration, and tumor angiogenesis of HeLa cells." (PMID 36176934, 2022). "There is evidence that endothelial cell-derived EVs influence tumor cells and for example, human brain microvascular endothelial-derived exosomes are thought to favor lung cancer tumor cell survival and resistance to apoptosis by increasing the levels of S100A16." (PMID 33738282, 2021). "Our research further clarifies the reason for declined ZO-2 in GC tumors, especially in tumor tissues with active proliferation and invasion, meaning S100A16 induces ZO-2 ubiquitination which is responsible for the abnormal ZO-2 degradation via ubiquitin-proteasomal system (UPS)." (PMID 34650982, 2021). "This identification suggests that the therapeutic targeting of S100A16 could increase ZO-2 protein level to inhibit tumor invasion and metastasis for the treatment of GC." (PMID 34650982, 2021). "To further evaluate the effect of S100A16 on GC cell migration and invasion in vivo, we constructed subcutaneous tumor formation experiments in nude mice using SGC-7901 cells stably infected with lenti-S100A16 or scramble control (lenti-S10016 or control group)." (PMID 34650982, 2021).
tumor (continued). "Of note, S100A16 protein expression at the tumor center did not reveal any association with clinicopathological variables." (PMID 26353754, 2015). "Experimentally, S100A16 was found to promote malignant keratinocyte differentiation and to suppress aggressive tumor phenotype such as proliferation, sphere formation and 3D-organotypic invasive abilities of OSCC-derived cells in vitro and tumorigenesis in a mouse xenograft model." (PMID 26353754, 2015). "S100A16 has also been shown to be ubiquitously expressed and upregulated in human tumor." (PMID 25642247, 2015). "Taken together, these findings suggested a role for S100A16 as a tumor suppressor in OSCC and indicated that progressive loss of S100A16 might be related with aggressive tumor growth and invasion leading to reduced patient survival." (PMID 26353754, 2015). "Indeed, retroviral mediated S100A16 over-expression significantly suppressed several aspects of aggressive tumor phenotype; such as proliferation, sphere formation and 3D-organotypic invasive abilities of OSCC-derived cells in vitro." (PMID 26353754, 2015). "In line with the mRNA results, S100A16 membrane-positive and nucleus-negative expression in LC has been reported to be associated with positive node status, higher T- and tumour stage, poor tumour differentiation, and poor prognosis." (PMID 37509106, 2023). "Therefore, whether S100A16 is regulated by LncRNA and plays a role in tumor may be the next potential research direction." (PMID 33912559, 2021). "Furthermore, across different stages of the mammary gland, S100A16 levels corroborated with dynamic remodeling that occurs during pregnancy and lactation—events that are suggested to be parallel to cellular and molecular changes that occur during tumor progression and metastasis." (PMID 40846689, 2025). "The tumor tissues and adjacent tissues from 92 NSCLC patients were collected to analyze the expression of miR-6884-5p and S100A16." (PMID 38271114, 2024). "The downregulation of thiosulfate transferase in BC promoted tumor invasion, migration, and the EMT, whereas the downregulation of S100A16 suppresses these processes." (PMID 37833982, 2023). "In parallel, expression of S100A16 was found to suppress tumorigenesis of OSCC cells in a mouse xenograft model, and the resulting tumour xenografts demonstrated features of increased differentiation and reduced proliferation/self-renewal." (PMID 37509106, 2023). "We further performed mechanistic experiments and rescue assays and demonstrated that S100A16 is the downstream of ADAMTS19, acting as a tumor promoter involved in carcinogenesis." (PMID 33921267, 2021). "Low S100A16 protein levels in OSCC significantly correlated with reduced 10-year overall survival and poor tumor differentiation." (PMID 26353754, 2015). "Further, correlation between reduced S100A16 expression level and reduced OSCC patient survival pointed towards a role for S100A16 in the maintenance of less aggressive tumor phenotype." (PMID 26353754, 2015). "Our results indicate a novel role for S100A16 in the regulation of OSCC differentiation and tumor suppression." (PMID 26353754, 2015). "In addition, correlations were also noted in the tumor array between S100A11 and S100A2 (R = 0.54), S100A4 (R = 0.46), S100A6 (R = 0.49), S100A13 (R = 0.67), S100A14 (R = 0.65), and S100A16 (R = 0.78)." (PMID 37627239, 2023). "Furthermore, we also concluded that down-regulated of S100A6 (F = 3.52, P=0.0164), S100A10 (F = 5.36, P=0.0015), S100A16 (F = 6.69, P=0.00027), and SDC1 (F = 4.02, P=0.00849) were effectively related to lower tumor stage." (PMID 35342420, 2022). "Although previous studies have reported that S100A16 tends to act as a tumor promoter, none examined the correlation between S100A16 expression and clinicopathological characteristics of GC." (PMID 33921267, 2021).
tumor (continued). "Further molecular characterization of S100A16 mediated tumor suppressive functions might contribute to the better understanding of OSCC carcinogenesis and provide opportunity for S100A16 based better prognostication and management of OSCC." (PMID 26353754, 2015). "The clinicopathological analysis of the current study showed a significant correlation between low S100A16 protein (at the invading front/island) levels and reduced 10-year overall survival probabilities for OSCC patients, poor tumor differentiation and positive cervical nodes." (PMID 26353754, 2015). "S100A16 staining was very weak or absent in the infiltrating tumor islands of positive cervical lymph nodes." (PMID 26353754, 2015). "The shorter period of CSS and RFS in this study could be attributed to tumor aggressiveness by EMT; however, the association of S100A16 and EMT in BC has not been elucidated." (PMID 37833982, 2023). "However, in the tumor array, positive correlations were observed between S100A14 and S100A2 (R = 0.50), S100A4 (R = 0.55), S100A6 (R = 0.45), S100A7 (R = 0.47), S100A11 (R = 0.65), S100A16 (R = 0.57) and S100P (R = 0.66)." (PMID 37627239, 2023). "We found that S100A16 did not affect MST1/2 expression, but decreased LATS1 protein and MOB phosphorylation, which allowed YAP to enter the nucleus triggering the downstream targets CYR61 and CTGF, which are known to stimulate the angiogenesis and tumor growth 29,30." (PMID 37151881, 2023).
infection (4 papers, 2014 to 2021). The state of being infected such as from the introduction of a foreign agent such as serum, vaccine, antigenic substance or organism. "S100A16 overexpression in HK-2 cells by infection with Lenti-S100A16 also induced upregulation of ER stress markers, including GRP78, p-IRE1α, and XBP1s." (PMID 34645789, 2021). "There were 10 common downregulated transcripts with a further six being unique to the synchronised infection (i.e., Hist4h4, 2900010M23Rik, Churc1, Rps15a, Lgals1, S100a16)." (PMID 31546628, 2019). "The protein levels of S100A16 were elevated after infection with pLV-S100A16 lentivirus." (PMID 25287362, 2014).
kidney disease (4 papers, 2020 to 2024). "The pathogenic relevance of S100A16 in renal disease was further assessed by immunostaining of kidney samples from UUO mice, a commonly used animal model of interstitial fibrosis." (PMID 32094322, 2020). "In recent studies using animal models, researchers have explored the potential implications of S100A16 in kidney disease and renal function." (PMID 38710691, 2024). "S100A16 is also involved in the regulation of kidney disease or renal function." (PMID 38710691, 2024). "Moreover, S100A16 was also highly expressed in kidney biopsy specimens from patients with various forms of clinical nephropathy." (PMID 34645789, 2021). "However, the reasons why S100A16 highly expressed in renal disease are still unclear." (PMID 38710691, 2024). "In sum, S100A16 is an interesting protein that may have significant implications in renal disease." (PMID 38710691, 2024).
metabolic disorders (1 paper, 2024). "Furthermore, there are indications that S100A16 might be involved in metabolic regulation and could potentially impact the pathogenesis of metabolic disorders." (PMID 38710691, 2024).
S100A16 also shares sentences with these, for which no sentence is quoted: cervical squamous cell carcinoma (3 papers); chronic kidney disease (3); colon adenocarcinoma (2); endocervical adenocarcinoma (2); Kidney Chromophobe (2); melanoma (2); acute lymphoblastic leukemia (1); adenocarcinoma (1); adrenocortical carcinoma (1); Alcohol- (1); bladder urothelial carcinoma (1); cardiac hypertrophy (1); cholesteatoma (1); depression (1); esophageal squamous cell carcinoma (1); focal segmental glomerulosclerosis (1); invasive breast carcinoma (1); low grade glioma (1); Lung squamous cell carcinoma (1); metastatic cancers (1); non-small cell lung adenocarcinoma (1); osteoporosis (1); ovarian serous cystadenocarcinoma (1); pancreatic diseases (1); Parkinson disease (1); prostate adenocarcinoma (1); psychiatric disorder (1); rectal cancer (1); rectum adenocarcinoma (1); scleroderma (1).
A further 5 diseases each share a sentence with S100A16 in 1 paper.